APP (amyloid beta precursor protein)
Diseases named in the same sentence as APP in open-access papers (continued):
Sharing a sentence is not in itself a finding about the gene and the disease.
amyloid (continued). "The AD mouse models, such as the popular 5xFAD, APP/PS1, or hAPPsl mouse lines, are designed to mimic amyloid pathology, whereas others, such as the PS19 mouse exhibit tau pathology, and others such as the 3xTg model show both." (PMID 41235867, 2025). "Mechanistic insight from APP/PS1 mice shows that Hbb expression rises with age and amyloid pathology, where it binds amyloid-β via its heme group and promotes plaque formation." (PMID 41180815, 2025). "Following the adoptive transfer of the engineered cells, APP/PS1 mice showed improvements in cognitive functions and a reduced amyloid load." (PMID 41009574, 2025). "The APPswe/PS1dE9/Blg (APP/PS1) model is widely used to evaluate such structural biomarkers, as amyloid plaque density and distribution that directly correlate with cognitive impairment and neurodegeneration severity." (PMID 41300242, 2025). "Similar findings have been reported in APP/PS1 mice, where autophagic activation in neurons and microglia alleviated amyloid pathology and cognitive impairment through the AMPK/mTOR/ULK1 pathway." (PMID 40589337, 2025). "Moreover, MGO-derived AGEs have been shown to upregulate APP and Aβ expression, thereby contributing to various memory deficits associated with brain dysfunction, indicating that tRES-HESP may mitigate amyloid-related neurotoxicity, thereby preserving neuronal function." (PMID 40362855, 2025). "As a model of cerebral amyloidosis, the APP/PS1 mouse model was used, which develops amyloid pathology starting at 5 to 6 months of age." (PMID 40145102, 2025). "Transduction of the Lenti-EGFP-SUMO1 vector to the hippocampus of APP/PS1 mice reduces the amount of Aβ and amyloid plaque, decreases the expression of sAPPβ and BACE1, but increases the expression of sAPPα." (PMID 41023583, 2025). "MAPT, APP, PSEN1, and BACE1 are key proteins involved in the pathological hallmarks of AD, namely neurofibrillary tangles and amyloid plaques." (PMID 41195325, 2025). "Activation of p75NTR and sortilin pathways enhances BACE1 expression and trafficking and induces APP phosphorylation and localization into endosomes through JNK activation, thereby maintaining a vicious cycle of amyloidosis and neurodegeneration." (PMID 40387258, 2025). "With implications for its function when iron interfaces with brain levels of APP and amyloidosis in AD, this work detailed how iron regulatory protein (IRP1) and miR-346 interact to bind and modify the activity of the APP IRE mRNA." (PMID 40438504, 2025). "The prominent role of APP as a network hub in both PD and MSA-P suggested involvement in synucleinopathy pathogenesis beyond amyloid-related mechanisms." (PMID 40993824, 2025). "The study focused on pathological and structural alterations of the primary visual pathway in 3–9-month-old APP/PS1 mice and their WT controls across three key stages—prior to amyloid plaque formation, at plaque onset, and during plaque enrichment." (PMID 41226060, 2025). "In this study (showing study design and profiling strategy), we profiled the brains of 5 month-old APP/PS1 mice, an age characterized by early amyloid deposition and gliosis." (PMID 41439990, 2025). "Hence, our newly generated mouse model overexpressing meprin β in astrocytes cannot be considered as a classical AD mouse model due to the lack of amyloid plaque deposition and strong memory deficits, but it does show increased AD-like pathological APP processing and AD-associated behavior." (PMID 38480559, 2024). "APP/PS1 transgenic AD mice, a widely used mouse model of AD with age-related pathological processes, and have obvious amyloid plaque formation starting at 8 months of age23." (PMID 38866763, 2024). "IL-33 administration into APP/PS1 mice has been shown to reduce soluble Aβ levels and amyloid plaque deposition by promoting the recruitment of microglia for enhancing Aβ phagocytic activity." (PMID 39548583, 2024).
amyloid (continued). "Humanin P3S binds to APOE4 and, upon administration to APP/PS1/APOE4 TR model mice, reduces amyloidosis." (PMID 38520065, 2024). "When the level of CTGF was reduced in APP/PS1 transgenic AD mice by tauroursodeoxycholic acid (TUDCA) supplemented, hippocampal and prefrontal amyloid deposition were decreased, and the spatial, recognition and contextual memory defects were also prevented." (PMID 38866763, 2024). "Our previous work showed that peripheral monocytes/macrophages are recruited to amyloid plaques in the APP/PS1 transgenic mouse model of AD, where they attenuate amyloid plaque load." (PMID 38516884, 2024). "However, the results from the forest plots may inspire future investigations when attention is drawn to the related biomarkers regarding amyloidosis (hence, Aβ is a product of sequential cleavage of the membrane glycoprotein APP (amyloid precursor protein) by β- and γ-secretases)." (PMID 38227084, 2024). "Our findings revealed statistically significant differences in the APP/PS1 mouse models, both prior to Aβ deposition during amyloid plaque formation with p‐values of ***0.003 and ****0.0001, respectively." (PMID 38967283, 2024). "Under pathological conditions, Aβ is the proteolytic product of the amyloid precursor protein (APP) produced by β-secretase (BACE1) and γ-secretase through the amyloidosis pathway." (PMID 39595941, 2024). "Consistent with the increased levels of Aβ peptides in Spi1+/−;APP/PS1 mice, we detected a 1.76- and 2.59-fold increase in amyloid plaque burden in the cortex and hippocampus, respectively, in Spi1+/−;APP/PS1 mice compared to Spi1+/+;APP/PS1 mice." (PMID 38734693, 2024). "Following on from the observation that ALA attenuated cognitive deficits and amyloidosis in APP23/PS45 transgenic mice, further analysis in 20E2 cells showed that ALA mediated an increase in the cleavage of APP by ADAM10 α-secretase." (PMID 39030577, 2024). "The hippocampus which is involved in the spatial and non-spatial recognition memory was stained to evaluate the amount of Aβ1-42 plaque in the APP/PS1 and control animals prior to and during the onset of amyloid pathology." (PMID 38862757, 2024). "APP/PS1 transgenic mouse models overexpress the human mutant forms of APP and PS1, and exhibit age-dependent aggravation in amyloid pathology and cognitive impairments similar to that observed in human AD brains." (PMID 38572429, 2024). "The therapeutic efficacy of 5a was evaluated in AD mice with scopolamine-induced memory impairment and APP/PS1 by analyzing cognitive function, glial reactivity, and amyloid pathology." (PMID 39431021, 2024). "In Aβ-treated astrocytes and aged AD APP/PS1 mouse model, the astrocytic C3 level elevates, suggesting that the astrocytic complement system is involved in amyloid pathology in AD." (PMID 38916729, 2024). "The enhanced protein level of LC3B-II and reduced SQSTM1 in the brain of 5xFAD mice injected with Fe65-EXO-Cory-B established its ability to augment autophagy, leading to the decreased level of APP-CTF, Aβ and amyloid plaque in the brain of 5xFAD mice." (PMID 37867176, 2023). "Increased Aβ plaques in the brain after consumption of a high fat diet has been observed in the APP/PS1, 5XFAD, APP23, and APPNL−F models of amyloidosis." (PMID 36721148, 2023). "UMI-77 normalized mitochondrial morphology and induced mitophagy in APP/PS1 mice triggering a rescue of learning and memory capacities, a reduction of the amyloid pathology and of neuroinflammation." (PMID 35665766, 2023). "The pathogenesis of AD occurs via the change of neuronal proteins, like amyloid precursor protein (APP) and Aβ peptide which form amyloid plaques in the brain cortex and hippocampus regions." (PMID 37153428, 2023).
amyloid (continued). "Here we examined the effects of BCI-838, PE, or the combination, in an additional AD mouse model (APP/PS1) that exhibits both oligomeric and fibrillar amyloid pathology." (PMID 39081972, 2023). "The involvement of η-secretase cleavage of APP in AD pathogenesis was supported by the finding that η-secretase and CTF-η are found within dystrophic neurites in close proximity to amyloid plaques." (PMID 38203429, 2023). "We administered a SIRT2 inhibitor to APP/PS1 mice, a model for AD, and found beneficial effects in the CNS: improved memory and learning, decreased amyloid pathology, and reduced neuroinflammation." (PMID 38132302, 2023). "We quantified changes in gene expression using total RNA extracted from FACS-isolated microglia of APP/PS1 and littermate control mice at 6 months of age, 4 months after tamoxifen treatment and when amyloid pathology is observable in the model." (PMID 36879321, 2023). "The amyloid burden and Aβ plaque load in the cortex and hippocampus of APPSwe/PS1∆E9 mice, together with APP metabolism and inflammatory responses, were investigated." (PMID 36982363, 2023). "Further, as APP and SAA are pivotal amyloid precursors participated in amyloidosis, their expressions in the brain were measured." (PMID 38115100, 2023). "We induced miR-155 deletion in microglia at 8-months of age in APP/PS1 mice, an age where amyloid plaque pathology is easily observed using antibodies (anti-6E10) directed against Aβ fibrils." (PMID 36879321, 2023). "A previous study demonstrated that THK-265 detected amyloid deposits in the brains of APP transgenic mice, and that the in vivo fluorescence intensity of THK-265 correlated well with the amyloid plaque burden." (PMID 37580462, 2023). "Translating-ribosome-affinity purification sequencing (TRAP-seq) was recently performed on the cortex of APP/PS1 mice, which develop amyloid pathology and astrogliosis." (PMID 37533101, 2023). "Given that APP and SAA are critical amyloid precursors involved in amyloidosis, their mRNA and protein expressions in the brain were detected in our study." (PMID 35457188, 2022). "On the one hand, the production and processing of the amyloid precursor protein (APP) was unchanged despite prolonged overexpression of the transgene, and the amyloid load was even reduced in hybrid IL-1β XAT and APP/PS1 Tg mice." (PMID 35163653, 2022). "Regarding the relevance of the APP/PS1 transgenic mouse as an experimental AD model, a previous study showed that impaired glucose tolerance and reduced insulin sensitivity precede amyloid plaque deposition and cognitive decline in these mice." (PMID 35875664, 2022). "We studied the effect of such intervention in two age cohorts of APP/PSEN1 and wt male mice; 4-month-old (appearance of the first amyloid plaques) and 10-month-old (fully developed amyloid pathology)." (PMID 35852609, 2022). "In an APP/APOE knockout mouse, inhibition of the TGFB/SMAD2 pathway activity in astrocytes has been shown to increase amyloid plaque formation and cognitive impairment." (PMID 35573689, 2022). "In old APP/PS1 mice, amyloid was observed in EPS regions, as shown in an orthogonal confocal image, and was seen in all PAS types including in peri-arterial and peri-arteriolar areas that lacked any significant pial coverage." (PMID 35794106, 2022). "βHB modulated β-amyloid precursor protein (APP) and neprilysin (NEP) expression mediated by GPR109A to suppress the amyloid plaque formation in 5xFAD (familial AD) mice." (PMID 35855338, 2022). "Based on these results, 4c was further evaluated in 3 x Tg mice and APP/PS1 mice, which present typical Tau pathology and amyloid-dependent pathology, respectively." (PMID 36698780, 2022). "Among different Nmnat isoforms, we identified hNmnat1 as a potent inhibitor for APP aggregation as evidenced by a remarkable reduction of the processed APP-CTF and decreased number and size of amyloid plaques in the brain." (PMID 35401143, 2022).
amyloid (continued). "Pathologically, amyloid β (Aβ) is produced by processing from amyloid precursor protein (APP) and extracellularly deposited as amyloid plaques." (PMID 34194300, 2021). "Accordingly, we overexpressed POMC protein in POMC neurons in the CA3 region in APP/PS1 mice at 8 months of age, when amyloid plaque deposition is extensive in the brain." (PMID 33623128, 2021). "In a time-course study, APP/PS1 mice had decreased gut diversity and distinct changes in inflammation-related bacteria, such as Akkermansia, before exhibiting amyloidosis and plaque-localized neuroinflammation." (PMID 34912029, 2021). "Sham-irradiated APP/PS1 females had significantly higher percent ROI of CD68 immunoreactivity than sham-irradiated APP/PS1 males (p = 0.0008), likely due to higher amyloid plaque load." (PMID 34948098, 2021). "Aβ-Th17 cell treatment affected amyloid load and microglial responses in APP/PS1 mice brain to a lesser extent compared to Aβ-Th1 cells which might be due to their less extensive inflammatory responses as those induced by Aβ-Th1 cells in an amyloid-rich environment." (PMID 34798897, 2021). "The 5xFAD model expresses three different APP genes and two different PS1 genes, and is particularly aggressive, developing amyloid lesions at only 2 months." (PMID 35053797, 2021). "In lab settings, [18F]FDG PET have been assessed along with Aβ imaging in various amyloidosis rodent models such as APPswe mice, 5 × FAD, APP/PS1, 3 × Tg, Tg4-42, TASTPM mice, and McGill-R-Thy1-APP rats." (PMID 34832961, 2021). "The sex-related decrease in phagocytosis is associated with an increase in amyloid load in sections prepared from female APP/PS1 mice and this supports previous findings of increased amyloidosis in female APP/PS1 mice." (PMID 34112929, 2021). "Human AD brains, different from APP mice, show less P2Y12R immunoreactivity in the regions of both tau and amyloid pathologies." (PMID 33644757, 2021). "In the current study, using the amyloid-β AD model APP/PS1, we investigated circadian, metabolic and amyloid characteristics of female mice and the effects of NOB." (PMID 34356628, 2021). "The choice of APP and PS1 genes affects both disease severity and time of onset, typically developing amyloid lesions similar to those seen in AD by 7–8 months." (PMID 35053797, 2021). "Although extracellular Aβ deposits are common features of both APP mouse models and AD patients, the composition of Aβ plaques in APP-overexpressing mouse models (e.g. Tg2576, APP23) was different from amyloid plaques in AD patients." (PMID 33644757, 2021). "Here, we show that amyloid-beta-induced hyperexcitability of hippocampal inhibitory parvalbumin (PV) interneurons importantly contributes to neuronal network dysfunction and memory impairment in APP/PS1 mice, a mouse model of increased amyloidosis." (PMID 31431685, 2020). "Both neurons and astrocytes contributed about equally to the process of amyloidosis, as evidenced by FISH, using the APP probe." (PMID 32453744, 2020). "Amyloid beta (Aβ), which is produced by the cleavage of the amyloid precursor protein (APP) by β- and γ-secretase, is the main component of the amyloid plaques observed in the brains of Alzheimer’s patients." (PMID 32660121, 2020). "In the hippocampus, amyloid plaque density was increased in APP/PS1-Hfd mice, as compared to APP/PS1-NC animals, at both time points." (PMID 32555372, 2020). "Immunohistochemical analyses show that the distribution of Gal-3 overlaps with that of endogenous Aβ in APP/PS1 mice and partially overlaps with that of amyloid plaque." (PMID 31127200, 2020). "APP/PS1 transgenic mice were crossed with PV-Cre transgenic mice, generating an APP/PS1-PV-Cre mouse model that allows for the specific detection and genetic manipulation of PV interneurons in a progressive amyloidosis background." (PMID 31431685, 2020).
amyloid (continued). "Using in situ hybridization, we demonstrated the expression of APP RNA in the astrocytes of SIV-infected macaque brains, thus underscoring the process of astrocytic amyloidosis in the archival brain sections of SIV-infected macaques." (PMID 32453744, 2020). "Since APP/PS1 mice were considered as the ideal model for analyzing amyloidosis in the pathogenesis of AD, effects of BaP exposure on amyloidosis were elucidated by immunohistochemistry, Thioflavin-T (ThioT) stain, and Western blot assays." (PMID 32867800, 2020). "First, we assessed the presence of the amyloid plaques in the cortex of 2 months old and 7 months old FAD+ mice using both the 6E10 antibody (staining for human APP) and the thiazine-red staining (staining for fibrillar Aβ)." (PMID 33132837, 2020). "Because astrocytes are key players in the pathogenesis of AD, we studied here if and how ES affects astrocytes in wildtype (WT) and APP/PS1 mice and how these relate to the previously reported amyloid pathology and microglial profile." (PMID 32197653, 2020). "Accordingly, we analyzed the microglial proteome at distinct stages of Aβ pathology in two commonly used mouse models of amyloidosis; the APPPS1, and the APP-KI mice." (PMID 32510331, 2020). "Our data show that in APP/PS1 mice at 15–17 weeks of age, which lack amyloid plaque pathology but do show increased brain levels of Aβ and hippocampus-dependent memory impairments, neuronal hyperexcitability is primarily observed in interneurons." (PMID 31431685, 2020). "In TDP-43-injected APP/PS1ΔE9 mice, TDP-43 impaired spatial memory and increases Aβ-related pathologies, including amyloid plaque burden, Aβ assembly, and microgliosis." (PMID 33230138, 2020). "Compared to APP21 rats, APP+PS1 rats had approximately two times the level of Aβ and more severe amyloid pathology, as well as memory and learning deficits that resembled AD." (PMID 33014535, 2020). "To investigate the effect of differential CLU levels on amyloid pathology, we first evaluated the CLU localization in APP/PS1 mice and human AD brain." (PMID 33246484, 2020). "While the exact function of reactive astrocytes is still not fully understood, genetic deletion of Gfap and Vimentin increased plaque load in APP/PS1 mice, suggesting that acquiring a reactive phenotype supports astrocytes in limiting amyloid pathology." (PMID 32197653, 2020). "Previous studies have also observed similar protective effects in APP/PS1 AD mice, where memory was preserved, LTP in the hippocampus normalized, and amyloid plaque load reduced." (PMID 31960630, 2020). "We first sought to identify the pathways that were specifically dysregulated in the 8-month-old amyloidosis mouse model and performed GSEA on the list of genes that were differentially expressed in the APP/PSEN1 mice in comparison to WT mice (FDR < 0.05)." (PMID 30283032, 2019). "Transgenic animals, like APPswe/PSEN1dE9 (APP/PS1) mice, reveal early and progressive accumulation of amyloid and develop memory decline, similar to symptoms in humans, from about 3 months old22." (PMID 31520077, 2019). "It is interesting that in mouse models of amyloid over-production (e.g., APP/PS1), there is evidence of a direct correspondence between amyloid deposition and iron deposition, while the distribution of iron in human amyloid deposits is far more heterogeneous." (PMID 31658742, 2019). "A recent study used the APP/PS1 mouse and an in vitro system to demonstrate that the interaction between CAPON with nNOS is enhanced under amyloid pathologies, and that this facilitates neuronal toxicity." (PMID 31160584, 2019). "Induction of systemic disorders such as osteoarthritis in APP/PS1 mice led to glial activation and exacerbation of amyloid pathology." (PMID 30953557, 2019). "APP/PS1 mice cognitive–behavioral changes occur at 3 months of age, APP/PS1 mice have a substantial number of amyloid deposits by 6 months of age." (PMID 31607908, 2019).